HSPB1 (heat shock protein family B (small) member 1)
Diseases named in the same sentence as HSPB1 in open-access papers (continued):
Sharing a sentence is not in itself a finding about the gene and the disease.
cancer (continued). "The majority of upregulated proteins have been previously linked to tumorigenesis or cancer homeostasis, including signaling molecules (integrin αV, GNAQ, GNA11, the latter two being associated with UM tumorigenesis), molecular chaperon (HSPB1), and an ESCRT-I complex subunit (i.e., TSG101)." (PMID 33050649, 2020). "In conclusion, we present evidence that HSPB1 silencing may improve cancer cell thermosensitivity when in combination with hyperthermia and have clinical potential in cancer treatments." (PMID 27626679, 2016). "When overexpressed in cancer HSPB1 is related to poor prognosis, tumour progression and metastasis." (PMID 27626679, 2016). "HSPB1 implications in cancer cell resistance to adriamycin has been debatable." (PMID 25818003, 2015). "Indeed, depletion of HspB1 expression in cancer cells induces a senescent-like phenotype characterized by several morphological changes." (PMID 24514166, 2014). "Hence, by protecting translational initiation HspB1 can indirectly enhance cancer cell survival through an efficient translation of mRNAs encoding polypeptides." (PMID 24514166, 2014). "Hence, HspB1 inhibition of drug-induced apoptosis by further enhancing HspB1 expression also increases the cellular resistance to many anti-cancer drugs." (PMID 24514166, 2014). "We hypothesized that a possible mechanism by which TNBC exhibit increased aggression and resistance to chemotherapy as compared to other cancers is, in part, due to the high expression of mouse and human HspB1." (PMID 22452810, 2012). "Moreover, in cancer cells, HspB1 is necessary for F-actin-mediated cytokinesis and therefore, interferes with the accumulation of giant polynucleated cells." (PMID 24278676, 2012). "The origin of these microparticles is unknown, but they could be exosomes, hence, suggesting that HspB1 is released from cancer cells by a mechanism close to that of Hsp70." (PMID 24278676, 2012). "Notably, the involvement of the HSF1/HSPB1 pathway in ferroptosis in cancer has been established." (PMID 39223962, 2024). "This suggests that in pan-cancers, HSPB1 may be involved in the regulation of the immune system." (PMID 37241117, 2023). "Additionally, HSPB1 expression is eliminated when HSPB6 is present in different cancer cell lines, and the interruption of heterodimer formation between HSPB1 and HSPB6 may lead to disease severity." (PMID 37241227, 2023). "Therefore, when cancer cells contain abnormally elevated iron and HSPB1, if HSPB1 pathway is down regulated, cells may be prone to ferroptosis." (PMID 35478955, 2022). "Hence, it is urgently interesting to address whether cancer HspB1 therapies are compatible, have a positive effect or, at least, are not deleterious with future CF treatments." (PMID 33923911, 2021). "However, HSPB1 knockdown increases erastin-induced iron uptake in cancer cells." (PMID 34335189, 2021). "Hspb1 as a diagnostic marker are not so much informative, but they are expedient indicators for carcinogenesis in some tissues and predict the differentiation and aggressiveness of few cancers." (PMID 28959337, 2016). "In addition of protecting against programmed cell death, HspB1 can also counteract other host anti-cancer responses, such as the oncogene-induced senescence (OIS) pathway that acts as roadblock in cancer development but which is often lost upon cancer progression." (PMID 24514166, 2014). "Finally, HSPB1 fragment levels in the blood of cancer patients may be a valuable prognostic marker of MMPIs." (PMID 24465581, 2014). "Indeed, recent observations clearly favor an important role played by HspB1 at the level of the cellular matrix suggesting that the relation between cancer cells and the normal cells that form the niche where the tumor grow is under the influence of small Hsps." (PMID 24514166, 2014). "However, the precise role of HSPB1 in cancer remains unclear." (PMID 42208896, 2026).
cancer (continued). "CDKN1A, EMC2, FDFT1, HSPB1, and MT1G were assessed for their ability to serve as prognostic indicators in pan-cancer by utilizing the TCGA database." (PMID 40432442, 2025). "The expression of mRNA of CDKN1A, EMC2, FDFT1, HSPB1, and MT1G in the TCGA and GTEx datasets were evaluated through the analysis of pan-cancer." (PMID 40432442, 2025). "Conversely, heat shock protein family B (small) member 1 (HSPB1, also known as HSP25 or HSP27) inhibits iron uptake by remodeling the cell cytoskeleton, thereby impeding ferroptosis in human cancer cells (e.g., HeLa, U2OS, and LNCaP)." (PMID 38844964, 2024). "Both HSPB1 and HSP90 have been reported to be up-regulated in many cancers, including lung, liver, pancreatic, breast and prostate cancer." (PMID 38167612, 2024). "HSPB1 stimulated the activity of matrix metalloproteinase 2 (MMP-2) through the TGF-β pathway, driving the migration of cancer cells from the prostate gland which is the prerequisite of distant metastasis." (PMID 37010714, 2023). "Previous studies have demonstrated the pivotal inhibitory effects of HSPA5, HSPB1, HSF1 and HSPH1 in cancer ferroptosis." (PMID 38041016, 2023). "In cancer cells, erastin, a particular iron apoptosis-inducing chemical, increases heat shock factor 1 (HSF1)-dependent HSPB1 expression." (PMID 38274225, 2023). "The best-known is HSP27 (HSPB1, HSP25, or HSP28), which is cytoplasmic but can translocate to the nucleus under stress, and it has been reported to be involved in cancer development." (PMID 36765939, 2023). "Among the upregulated proteins, we found that most were cancer-related proteins such as S100 family proteins, SFN, LDHA, and HSPB1, which all play important roles in tumor migration and invasion." (PMID 35936690, 2022). "However, despite the many findings in recent years that have contributed to understanding the mechanism of action of HSPB8 and HSPB1 in response to proteotoxic events, some aspects of their regulation and function, as well as its implication in human cancer, remain partially unknown." (PMID 36233058, 2022). "Malignant cell clusters shared cancer characteristics and widely significantly overexpressed HLA-A, HLA-B, MCL1, HDAC1, LCK, HSPB1, and IL6R, indicating a common tumor origin." (PMID 36131282, 2022). "HSP27 (HSPB1) is a member of small HSP family aberrant expression of which correlates with poor prognosis and resistance to chemotherapy in different types of cancer." (PMID 34917098, 2021). "The expression levels of JUN, SFN, HSPB1, and CD47 in cancer cells and the expression levels of KLRB1, CD48, GZMK, and LY6E in CD8+ T cells were consistent with the scRNA-seq results." (PMID 33083004, 2020). "Though high expression of sHSPs has been reported in many cancer types, several studies have focused on HSP27 or HSPB1 which is considered as a central sHSP in relation to PCa." (PMID 31426412, 2019). "Stepwise Cox regression modelling suggested that the methylation of genes HSPB1, CCND2 and DPYS contributed objective prognostic information to Gleason score and PSA with respect to cancer-related death during follow-up (p = 0.006)." (PMID 25193387, 2014). "A subset of the targets (BCL2, CLU, HSPB1, BIRC5, EIF4E and RRM2) is being investigated for cancers in combination with approved cytotoxic drugs." (PMID 22989709, 2012). "In solid cancer tissues, the HSPB1/p38 MAPK and HSPB1/ERK1/2 (p42/p44 MAPKs) pathways were activated, and activation of the HSPB1/MAPKs conferred tumour cells with resistance to ferroptosis and contributed to cancer progression." (PMID 38682349, 2024). "The specific role of HSPB1 in ferroptosis in CRC cells remains unclear, but studies have suggested that the expression of HSPB1 can inhibit ferroptosis in other cancer cells." (PMID 37842645, 2023). "Moreover, HSPB1 was also found to be up-regulated in NSCLC and other types of cancers and was positively correlated with that of AS-tDR-007333 in NSCLC tumor tissues." (PMID 35526007, 2022).
cancer (continued). "Protein expressions of HMOX1, HSPB1 and NCOA4 were markedly decreased in cancer tissues." (PMID 33996565, 2021). "The correlation between HspB1 expression in RCC subtypes and metastasis process has been revealed in previous studies and HspB1 is known to facilitate metastasis by suppressing anti-cancer response such as apoptosis and senescence." (PMID 33672271, 2021). "HSPB1 has neuroprotective and anti-apoptotic functions and is not only frequently reported in cancers, but also has a close relationship with central nervous system diseases." (PMID 34488523, 2021). "Consequently, among HspB1’s interacting proteins, there are surely some proteins that contribute to CSC-driven cancer development or are responsible for the manifestation of certain properties of CSCs." (PMID 32927696, 2020). "Heatmap of differential gene expression in GGN-ADC and SADC showed that some cancer-promoting genes, such as HSPB1, CCL2, CXCL14, MDK, and MMP7, were highly expressed in SADC, indicating that the cancer cells derived from SADC had a higher malignant degree than those derived from GGN-ADC." (PMID 33083004, 2020). "Seven out of 52 genes (GSTP1, HSP90B1, HSPB1, PFN1, RAP1A, SFN, YWHAZ) were assigned to KEGG pathways in cancer, cell migration and cell cycle, and in signaling networks involved in proliferation, cellular motility, apoptosis, cell adhesion, angiogenesis and genetic integrity." (PMID 30157864, 2018). "Also known as HSPB1, it is a small HSP that plays an essential role in the cytoprotection in cancer, and is inducible by various stimuli such as hyperthermia." (PMID 27626679, 2016). "Consequently, a geneticaly induced downregulation of HspB1 up-regulates PTEN level and blocks the survival pathway of cancer cells." (PMID 24514166, 2014). "Another worth noting negative point concerns HspB1 ability to provide cancer cells with resistance to many anti-cancer drugs, which in turn, unfortunately, stimulates HspB1 expression." (PMID 24278676, 2012). "Immunohistochemical analysis of HSPA1A/B expression revealed similar expression of HSPB1 in early prostate cancers compared with non-neoplastic controls, but diminished expression was noted in morphologically advanced cancers." (PMID 24213112, 2011). "In addition, previous studies have demonstrated that HSPB1 inhibits the ferroptosis process in various cancer cells, but its role in CRC has not been reported." (PMID 38041016, 2023). "Among the proteins with anti-cancer effects, the upregulation of HSPB1 (heat shock protein beta-1) could indicate some resistance of the cancer cells and the absence of apoptosis in the cells treated with C.cicadae." (PMID 34771120, 2021). "No doubt, HspB1 is one of the most promising targets for CSC-based cancer treatment." (PMID 32927696, 2020). "For example, heat shock protein beta-1 (HSPB1) and CDGSH iron sulfur domain 1 (CISD1) are both negative regulators of ferroptotic cancer cell death." (PMID 33537073, 2021).
tumor (118 papers, 2009 to 2026). "Ultimately, we examined the association between HSPB1 manifestation intensities and factors related to tumor immunity, such as immuno‐stimulator, immuno‐inhibitor, MHC, receptor, and chemokine." (PMID 41497799, 2025). "More importantly, many of the downregulated genes (Fn1, Hspb1, Postn, Mia, Fgfr1, Serpine2) have been associated with tumor metastasis." (PMID 39287984, 2024). "In breast cancer, non-small cell lung cancer, gastric cancer, and prostate cancer, aberrant expression levels of HSPB1 have been associated with aggressive tumor behavior, chemotherapy resistance, and poor prognosis." (PMID 39397802, 2024). "We found that only HSPB1 expression was weakly negatively associated with Gleason score (P value = 0.095) and tumor stage (P value = 0.136)." (PMID 26158290, 2015). "High levels of mouse HspB1 have been shown to be associated with increased tumor growth and high metastatic potential." (PMID 22452810, 2012). "Whereas the co-expression of HSPB1 and CD31 was prominent in non-fibrotic regions, vessels co-expressing HSPB1 and CD31 were scarce in fibrotic regions, suggesting that HSPB1 deficiency may contribute to tumor fibrosis." (PMID 41154806, 2025). "Moreover, high levels of circulating HspB1 are also associated with tumor progression and increased postinjury infection." (PMID 24278676, 2012). "This work presented functional evidence linked to CAF biology—CAF-associated markers, increased collagen deposition, heightened tumor fibrosis, and enhanced tumor growth—and explicitly proposed that EndMT caused by HSPB1 deficiency could serve as a source of CAFs." (PMID 41154806, 2025). "Furthermore, the roles of molecules such as Coactivator Associated Arginine Methyltransferase 1 (CARM1)and heat shock protein family B (small) member 1 (HSPB1) in regulating ferroptosis further emphasize the importance of ferroptosis in the tumor immune microenvironment." (PMID 39273090, 2024). "Additionally, high HSPB1 expression was associated with poor prognosis in these tumours." (PMID 37241117, 2023). "The authors suggested that the role of HSPB1 in facilitating tumor invasion through angiogenesis in PitNETs presents a potential target for therapeutic intervention in cases of PitNETs that invade the cavernous sinus." (PMID 41614857, 2025). "Metabolomics analysis revealed that Hspb1 downregulation further promoted abnormal lipid metabolism in Hepa1-6 tumor-bearing mice, enhancing pro-ferroptosis effects of combination therapy." (PMID 41413253, 2025). "Meanwhile, Hspb1 downregulation further enhanced RT and IO-induced anti-tumor immune response in tumor-bearing mice, as evidenced by significantly elevated numbers of cytotoxic CD8 + T cells." (PMID 41413253, 2025). "Li and his team revealed that HSPB1 is a common factor that promotes tumor and endothelial cell proliferation and migration through VEGF/VEGFR pathway activation." (PMID 41614857, 2025). "In vitro and in vivo experiments further demonstrated that HSPB1-overexpressing CAFs enhance tumor cell malignancy, underscoring the therapeutic promise of targeting the HSPB1-CAF axis in CRC." (PMID 41407838, 2025). "The effect of IVM on HSPB1 phosphorylation was tested by studyingthe expression of p-HSPB1 in the tumor tissue 24 h after the lasttreatment." (PMID 39144564, 2024). "On IHC-stained tumor sections, p-HSPB1-positive areas werestained dark brown, which were masked with green for quantification." (PMID 39144564, 2024). "Immunofluorescence and immunohistochemistry assays showed that exosomes promoted the expression of HSPB1, FUS and ki‐67 in tumour tissues, and knockdown of HSPB1 reversed the effects of exosomes." (PMID 38682349, 2024). "Cleaving HSPB1 into fragments has a significant effect on tumor progression depending on the fragment." (PMID 39763976, 2024).
tumor (continued). "we observed that the tumour volume and weight were greater in nude mice injected with exosomes, and the knockdown of HSPB1 induced a decrease in the tumour volume and weight." (PMID 38682349, 2024). "On the other hand, HSPB1 phosphorylation protects tumor cells from ferroptosis by reducing lipid ROS production mediated by iron." (PMID 37138885, 2023). "Collectively, these results suggested that HSPB1 facilitated tumor growth, doxorubicin resistance, and metastasis in vivo." (PMID 37454220, 2023). "Erastin treatment can induce the activation of HSPB1 to trigger the ferroptosis resistance mechanism in tumor cells." (PMID 37723588, 2023). "This indicates that in tumour tissue species, high expression of HSPB1 inhibits the exercise of functions by most immune cells." (PMID 37241117, 2023). "To better understand the HSPB1’s immunological correlations, we performed the Spearman’s correlation analysis between HSPB1 protein abundance and tumor immune cell infiltration levels." (PMID 37158834, 2023). "It leads to the downregulation of HSPB1 phosphorylation, inhibits the activation of the HSPB1/p38 MAPK signaling pathway, and increases the susceptibility of tumor cells to ferroptosis." (PMID 36936418, 2023). "The role of HSPB1 in tumor immunity has been previously demonstrated, and its mechanism of action is related to the direct immunosuppression of Ym1 produced by macrophages and T cell suppression." (PMID 37405952, 2023). "The results showed that data from both the TIMER database and TCGA database showed that HSPB1 was significantly highly expressed in most tumours compared to normal tissue." (PMID 37241117, 2023). "According to recent studies, HSPB1 can form a p38/pMAPKAPK2/pHSPB1 cascade with p38/MAPKAPK2 in GC to encourage tumor growth and metastasis." (PMID 37016377, 2023). "HSPB1 encodes a member of the small heat shock protein (HSP27), and its expression has been demonstrated to inhibit the ferroptosis process of tumor cells, thereby promoting tumor growth." (PMID 36414988, 2022). "At early tumor stages, HSPB1 expression is inhibited, but it is re-expressed during PCa progression, leading to a more aggressive phenotype." (PMID 35204174, 2022). "For example, the overexpression of heat shock protein beta-1 (HSPB1) inhibits ferroptosis by reducing intracellular iron accumulation by inhibiting TRF1 expression in tumor cells." (PMID 36117534, 2022). "HSPB1 also inactivates the Hippo tumor-suppressor pathway and decreases the phosphorylation of YAP22." (PMID 36171217, 2022). "During the tumor-induced angiogenesis process, however, VEGF is overwhelmingly increased, yet the concomitant increase of HSPB1 is incapable of balancing the pathological angiogenesis, therefore contributes to tumor progression." (PMID 34670584, 2021). "It has been reported that HSPB1 (HSP27) can act as a tumor suppressor, and its downregulation has been reported as a therapeutic target for prostate cancer." (PMID 34578333, 2021). "HSP27 is also known as HSPB1 (heat shock protein family B number 1) and it is an important protein involved in drug resistance, cell growth, apoptosis, tumor occurrence, and metastasis, etc." (PMID 32246298, 2020). "Of interest here is that the PI3K/Akt signalling pathway is negatively regulated by PTEN and we have reported that PTEN is downregulated by HSPB1 (HSP27), both proteins have been implicated in HER2-positive tumours." (PMID 29954368, 2018). "In patients with a large main tumour size, the expression of HSPB1 and TRIP13 was increased compared to patients with a small main tumour size." (PMID 28266596, 2017). "The gene transcription of Calr3, Hspb1, and Tnfaip6, which are related to immunogenicity induction of dead cells, was up-regulated in the R2016 treated tumor cells." (PMID 28282460, 2017).